ATR (ATR checkpoint kinase)
Diseases named in the same sentence as ATR in open-access papers (continued):
Sharing a sentence is not in itself a finding about the gene and the disease.
infection (continued). "In order to determine differences in neutrophil responses in the ATR-deficient mouse strains, we used a hirudin-based whole blood model for ex vivo infection, as this anticoagulant does not interfere with complement activation or Nme growth." (PMID 31274379, 2019). "Furthermore, direct measurement of genome copy number by real-time PCR confirms that inhibition of ATR 1 hr before or after infection significantly decreases viral DNA replication." (PMID 28467896, 2017). "Numerous studies have demonstrated that HPV exploits both the ataxia-telangiectasia mutated (ATM) and ataxia-telangiectasia and rad3-related (ATR) DDR pathways to replicate its genome and maintain a persistent infection by downregulating the innate and cell-mediated immunity." (PMID 29257060, 2017). "ATR activation of CHK1, a major effector typically associated with S-phase and G2-phase cell cycle arrest in response to diverse DNA damage stimuli, is inhibited during MVM infection." (PMID 29088070, 2017). "JEM did infections with ATR and Chk1 inhibitors and sorting of infected cells for IF experiments." (PMID 28604764, 2017). "Consistent with this, inhibition of ATR decreases viral production 10-fold 8 hr post-infection." (PMID 28467896, 2017). "We also observed that ATM activation by dl366* infection of HeLa cells occurred earlier than ATR activation (represented by Chk1 phosphorylation), suggesting that ATR is activated and could exert its effect only at the later stages of infection." (PMID 26867009, 2016). "SV40 chromatin replication was highly sensitive to inhibition of ATR throughout a 48 h infection." (PMID 23592994, 2013). "However, our findings suggest that while ATR may be inactivated at late stages, it is required at the early stages of infection to establish viral replication centers in the nuclear compartment." (PMID 37376543, 2023). "Therefore, we hypothesized that ATR/CHK1 inactivation at late stages of infection dysregulates CDC7 and its ability to regulate new origin firing." (PMID 37253065, 2023). "Taking advantage of this, we examined the phosphorylation status of SQ/TQ motif-containing proteins in HeLa cells to investigate whether the ATR/ATM arms of the DNA damage response are activated by infection with the Western Reserve (WR) strain of vaccinia virus." (PMID 28467896, 2017). "To interrogate the role of phosphorylated H2AX in infection of human fibroblasts by HSV-1 and HSV-2, we inhibited ATM and ATR activity using three approaches: chemical inhibitors of ATM or ATR kinase activity, siRNAs specific for ATM and ATR, and cell lines deficient in either ATR or ATM." (PMID 26817608, 2016). "In contrast, the infection induced a significant reduction in body mass on day 1, an indicator of illness, compared to mock infection, which was abrogated by PD0325901 and ATR-002 treatment." (PMID 40422262, 2025). "DNA viruses, such as human bocavirus 1 (HBoV1) infection, induce a DDR with activation of ATM, ATR, and DNA-PKcs." (PMID 40008889, 2025). "To confirm that NS1 is an alternative marker for cellular DDR during all stages of MVM infection, we performed laser microirradiation followed by immunofluorescence for NS1 and phosphorylated CHK1, which is activated downstream of ATR/TopBP1." (PMID 37376543, 2023). "For example, Chikungunya and Sindbis viruses – members of the family Togaviridae that, like SARS-CoV-2 and other coronaviruses, replicate in the cytoplasm – activate ATR and PARP1 pathways following infection." (PMID 37948194, 2023). "Protoparvovirus minute virus of mice (MVM) infection activates the ATM pathway, ATR, and DNA-PKcs with its accessory proteins, i.e., the Ku70/Ku80 heterodimer, which accumulate in the virus replication centers, depending on the cell types." (PMID 34878919, 2022).
infection (continued). "To further evaluate the effect of these pathways on γ-H2AX expression, we treated RD cells with an ATR inhibitor (VE-821), DNA-PK inhibitor (KU 57788), or ATM inhibitor (KU 55933) at 2 h post infection with EVA71 (MOI = 2)." (PMID 35067196, 2022). "HBoV1 infection activates ATM, ATR and DNA-PK, which play significant roles in viral DNA replication." (PMID 34220786, 2021). "B cells infected with EBV have been reported to activate these stress-related pathways early after infection (16, –, 19), although more recent evidence indicates that EBV infection of B cells primarily activates the ATR/Chk1 pathway (16, –, 18)." (PMID 34781735, 2021). "Infection by Ra led to the formation of distinct nuclear pRPA2 and RPA2 foci and robust activation of ATR-Chk1 pathway, suggesting that Ra induces generation of ssDNA." (PMID 32223892, 2020). "Kinase-motif analysis reveals temporal activation patterns of certain protein kinases, with several CDKs/MAPKs immediately active upon the infection, and basophilic kinases, ATM, and ATR engaging later." (PMID 32859902, 2020). "Early during infection, SMARCAL1 was recruited to viral RCs through its interaction with RPA, and this recruitment was also regulated by ATR- and cyclin-dependent kinase (CDK)-dependent phosphorylation." (PMID 32906746, 2020). "We thus monitored ATR and ATM activation in HeLa cells collected 8 h after infection with DH10B hosting the BACpks or the vector or after treatment with mitomycin C (MMC)." (PMID 29559578, 2018). "Consistent with a role for activated ATR during infection, we found that Ser33 in RPA2, an ATR substrate, becomes phosphorylated in an ATR-dependent manner from 4 hr post-infection at the time of genome replication." (PMID 28467896, 2017). "The closely related BKV has also been reported to induce the DDR: infection of the natural host cells of the virus, renal proximal tubule epithelial (RPTE) cells, activated both the ATM and the ATR (ATM and Rad3-related) DDR." (PMID 28202068, 2017). "We already knew by WBs that the HO fusion protein varies little throughout the time course of infection, but its activity seems to be limited to the first hour, after which the enzyme is phosphorylated by ATM/ATR and appears to be inhibited." (PMID 24655462, 2014). "Infection with B19V induces a broad range of DNA damage responses by activating three upstream kinases: ATM, ATR, and DNA-PKcs." (PMID 24859341, 2014). "Infection of cells by polyomaviruses and papillomaviruses is accompanied by intense ATM and ATR activation." (PMID 25474690, 2014). "(2020) we here confirmed for a primary host cell type that ATM-mediated repair signaling is induced in T. gondii RH-infected BUVEC whilst the ATR-dependent pathway was not affected by infection." (PMID 38524184, 2024). "ATR was nuclear in uninfected cells but tended to be pan-cellular after HAdV-C5 infection; it also formed foci, although these did not correspond to VRCs." (PMID 38140597, 2023). "However, MVM infection inactivates the ATR/CHK1 pathway at late stages, suggesting that early in infection (12 hpi and 18 hpi) there is sufficient nuclear CHK1 to respond to replication stress and unscheduled origin firing." (PMID 37253065, 2023). "Interestingly, however, ATR, USP9, and USP34 were largely unaffected over a prolonged time course of infection." (PMID 38140597, 2023). "During infection with WT Ad5, ATR is recruited to viral RCs but is not activated, as determined by the low levels of Chk1 phosphorylation." (PMID 32906746, 2020). "The results showed that CCC DNA formation was suppressed by two ATR inhibitors (AZD6738 and VE-821) and the CHK1 inhibitor (CHIR-124), suggesting that the ATR-CHK1 pathway indeed played a critical role in HBV CCC DNA formation during de novo infection." (PMID 32071277, 2020).
infection (continued). "Taken together, these data strongly suggest that the modulation of the cell cycle mediated by Rck is dependent on the DDR process and notably the ATR and/or ATM pathways, which are triggered in response to the DNA damage generated in the host DNA upon infection." (PMID 33330131, 2020). "In accordance with the attenuated cytokine response in vivo, IL-6 responses in the ex vivo whole blood infection model showed a (non-significant) down-trend for all ATR-knockout mice compared to WT." (PMID 31274379, 2019). "Ultimately, the authors provided evidence that MRN is key in the hyperphosphorylation of ATR substrates following infection with Ad5 lacking E4, and that this can be abrogated through expression of Ad5 E4orf3 and subsequent mislocalization of the MRN complex." (PMID 28791251, 2017). "Single-strand nicks, which are normally another trigger of ATR activation, are generated during MVM infection and may be occluded by bound NS1." (PMID 29088070, 2017). "We attempted to restore viral replication in ATR-deficient GM18366D cells by transfecting a plasmid expressing wild-type ATR protein, but a strong interferon response to the transfected DNA led to reduced efficiency of infection (data not shown)." (PMID 26817608, 2016). "As expected, infection of PCV2 alone activated caspase-3 in the cultured cells, whereas their activities were significantly decreased in the infected cells when treated with the ATM, ATM/ATR, or DNA-PK inhibitor." (PMID 27982097, 2016). "Without helper viruses and any AAV2 protein expression, the infection of UV-inactivated AAV2 infection activates ATR by mimicking a stalled replication fork, and induces G2/M arrest and apoptosis." (PMID 26765330, 2016). "Therefore, the DDR-facilitating parvovirus DNA replication during infections of MVM, MVC, and B19 is likely a result of cell cycle arrest at the S/late S phase induced by ATM or ATR activation." (PMID 26765330, 2016). "Resection of these broken DNAs could activate ATR, providing for efficient S phase arrest of SV40 infected cells early during infection." (PMID 25474690, 2014). "We conclude that ATR contributes to S phase arrest of SV40 infected cells throughout infection, but does not affect viral replication center stability in the fraction of cells that remain arrested in S phase." (PMID 25474690, 2014). "One consequence of ATR inhibition was that infected cells continued to cycle throughout infection, rather than arresting in late S phase where viral DNA replication would be favored." (PMID 23592994, 2013). "Notably, while our data rule out canonical DDR factors (ATM, ATR, DNA-PK), they do not address the interplay between DNA damage during infection and Vpr-induced TGF-β production." (PMID 40632811, 2025). "Levels of ATM and ATR were unchanged regardless of infection." (PMID 41186411, 2025). "Notably, certain binding proteins, such as ATR and USP34, remain undegraded during infection." (PMID 38140597, 2023). "Our results show that the infection can also downregulate APE2, in a CagA-independent manner, which could potentially modulate the response to oxidative stress and SSBs by compromising the ATR/ Checkpoint Kinase 1 (CHK1) pathway." (PMID 33339161, 2020). "Interestingly, however, whereas ATR activity modulates p21 degradation in response to various DDR-inducing agents (as described more fully below), the activation of ATR and its substrate CHK1 is reduced during MVM infection, consistent with the independence of p21 signaling from this pathway." (PMID 29088070, 2017). "Following infection of human foreskin fibroblasts by HSV-1 or HSV-2, we assayed the phosphorylation of H2AX in the presence of inhibitors of transcription, translation, or viral DNA replication, or in the presence of inhibitors of ATM and ATR kinases (KU-55933 and VE-821, respectively)." (PMID 26817608, 2016).
infection (continued). "In vitro, it was found that P+ group could induce DNA damage in OSCC cells under short-term acute infection, which made γ-H2AX gradually accumulate with cell proliferation, activate the upstream signal molecule of ATR-CHK1, and increase the phosphorylation level of ATR and RPA2." (PMID 34660289, 2021). "Bocaparvovirus minute virus of canines (MVC) infection results in activation of both ATM and ATR cascades but not DNA-PKcs, and only ATM activation is required for efficient viral replication and progeny production." (PMID 34878919, 2022). "Consistent with resection mediating ATR activation early during infection, ATM inhibition prior to 20 hpi decreased ATR activation whereas inhibition from 20 to 48 hpi did not affect ATR kinase function." (PMID 25474690, 2014). "Infection of H-Lats with VprWT virus induced significantly higher eGFP expression compared to control infections, regardless of MOI, which could be ablated by caffeine or ATM/ATR-specific inhibitors." (PMID 39975144, 2025). "Vpr/VifIR-AA infected HeLa, THP1, or SupT cells were treated with vehicle, an ATM inhibitor (AZD1390), an ATR inhibitor (NU6027), or caffeine, and γH2AX foci were quantified 48-hours post-infection (note: these cells were not treated with a DNA damaging agent)." (PMID 37669285, 2023). "This suggested that the ATR, but not the ATM, pathway might be involved in HBV CCC DNA formation during infection." (PMID 32071277, 2020). "However, a reduction in phosphorylation of all tested Chk1 phospho sites was observed upon infection with dl366*+E4orf4, suggesting that ATM was not required for the reduced phosphorylation of ATR substrates induced by E4orf4." (PMID 26867009, 2016).
adenocarcinoma (6 papers, 2016 to 2024). A common cancer characterized by the presence of malignant glandular cells. "We observed a higher mutation frequency of NF1, ATR, and BRCA1 in EGFR-mutant SCC compared to EGFR-mutant adenocarcinoma." (PMID 34195081, 2021). "The extent of ATR N-homocysteinylation, correlated with Hcy levels in HCT116 and A549 adenocarcinoma cells, reduces ATR activity by impairing the ATR-ATRIP interaction, which results in DNA damage in CRC." (PMID 31252610, 2019).
neurological disorders (4 papers, 2020 to 2025). "Moreover, as cortical thickness is also associated with neurological disorders, we potentially can link genetic traits ATR-RASSF1A-actin to disruption of mechanotransduction, nuclear F-actin and neuronal plasticity, cortex depth, and psychiatric disorders." (PMID 39951537, 2025).
hematological malignancies (2 papers, 2019 to 2025). "Inhibition of ATR with an ATR inhibitor either as a monotherapy or in combination with DNA- damaging chemotherapy drugs, ionizing radiation, immune checkpoint blockers, or PARP inhibitors is being tested in early-phase clinical trials in advanced solid tumors and hematological malignancies." (PMID 31018854, 2019).
kidney disease (2 papers, 2024 to 2025). "Collectively, these findings highlight the potential of targeting DNA damage pathways, such as via restoring expression of repair factors like KAT5, ATR, FANCD2 and ERCC1 in kidney cells, as a therapeutic approach to slow down the progression of kidney disease in both tubular cells and podocytes." (PMID 38773208, 2024).
bacterial infections (1 paper, 2018). "However, it remained unclear if this inhibitor and its active form, ATR-002, might sensitize host cells to either IV or secondary bacterial infections." (PMID 29904167, 2018).
connective tissue disorder (1 paper, 2025). A disease involving the connective tissue. "The present case may represent a novel manifestation of ATR-related disorders, suggesting considerable overlap with hereditary connective tissue disorders." (PMID 41602232, 2025).
gynecological tumors (1 paper, 2021). "ARID1A deficient clear cell carcinoma of the ovary or endometrium is sensitive to ATR inhibition, while the combination of ATR and PARP inhibition has activity in other gynecological tumors, irrespective of ARID1A status." (PMID 34518240, 2021).
neurodegenerative disease (1 paper, 2024). A disorder of the central nervous system characterized by gradual and progressive loss of neural tissue and neurologic function. "Moreover, although it is well established that ATM or ATR mutations may lead to genomic instability, thereby promoting tumorigenesis, patients with ATM or ATR mutations are also reported to have neurodegenerative diseases." (PMID 38554113, 2024).
psychiatric disorder (1 paper, 2025). A disorder characterized by behavioral and/or psychological abnormalities, often accompanied by physical symptoms. "Together, our data support that ATR-hippo signaling is an important mediator of nuclear F-actin and the impact of an rs2073498 has a physiological impact supported by human genetic association with psychiatric disorders." (PMID 39951537, 2025).
ATR also shares sentences with these, for which no sentence is quoted: acute myeloid leukemia (5 papers); genetic disorder (5); primordial dwarfism (4); diffuse large B-cell lymphoma (3); myeloid leukemia (3); Nijmegen breakage syndrome (3); adenoid cystic carcinoma (2); alveolar rhabdomyosarcoma (2); Atr-Seckel syndrome (2); Burkitt lymphoma (2); colorectal (2); Eμ (2); kidney cancer (2); NBS-like disorder (2); neutropenia (2); oral cancer (2); acromegaly (1); acute kidney injury (1); adenoma (1); adenosarcoma (1); amyotrophic lateral sclerosis (1); anaplastic large cell lymphoma (1); ankylosing spondylitis (1); astrocytomas (1); autism (1); autoimmune disease (1); B-cell acute lymphoblastic leukaemia (1); benign tumors (1); bladder tumor (1); bone cancer (1).
A further 83 diseases each share a sentence with ATR in 1 paper.